COPS5 (COP9 signalosome subunit 5)
Diseases named in the same sentence as COPS5 in open-access papers (continued):
Sharing a sentence is not in itself a finding about the gene and the disease.
breast carcinoma (continued). "As one of the hub genes of breast cancer prognosis, COPS5, also known as JAB1 or CSN5, was initially identified as c-Jun activation domain-binding protein-1 and is aberrantly overexpressed in various human cancers including breast cancer." (PMID 34993131, 2021). "Actually, Jab1/COPS5 overexpression was reported in many kinds of cancers, including hepatocellular carcinoma (HCC), pancreatic cancer, breast cancer, non-small cell lung cancer (NSCLC), nasopharyngeal carcinoma (NPC), and many others." (PMID 29535627, 2018). "This study on breast cancer patients reveals that the changes in Jab1/COPS5 predict the DFS and OS; patients who had higher Jab1/COPS5 level had shorter DFS and OS than patients who had lower Jab1/COPS5 level." (PMID 29228627, 2017). "To further evaluate the role of COPS5 in a model system, we attempted to establish in vitro models derived from MCF7 ERα+ breast cancer cells that are highly resistant to 4-hydroxy-tamoxifen (4OHT, an active metabolite of tamoxifen) at up to 2 μM by a dose-escalation protocol (refer to Methods)." (PMID 27375289, 2016). "Finally, COPS5, HDAC2, and NONO were selected as hub TFs because of their significantly higher expression in breast cancer, lower survival probability in the high-risk group, and specific target genes." (PMID 34993131, 2021). "Breast cancer patients without Jab1/COPS5 expression did not recur or progression." (PMID 29535627, 2018). "Importantly, breast cancer patients with Jab1/COPS5-negative tumors had neither relapse nor disease progression at a median follow-up time of 70 months." (PMID 29383106, 2017). "Similarly, in another ERα+ breast cancer cell line T47D, we observed that overexpression of WT but not D151N COPS5 led to agonistic conversion of 4OHT in ERα-dependent transcription, and caused resistance to 4OHT-induced growth inhibition." (PMID 27375289, 2016). "Results of the TF–target gene network, expression panel, and survival analysis revealed that COPS5, HDAC2, and NONO served as the hub TFs for breast cancer." (PMID 34993131, 2021). "Consistent with the bioinformatics analysis, COPS5, HDAC2, and NONO were more highly expressed in breast cancer cell lines than in normal breast epithelial cells." (PMID 34993131, 2021). "COPS5, HDAC2, and NONO were recognized as hub TFs in breast cancer." (PMID 34993131, 2021). "Upon further analysis, three hub TFs, COPS5, HDAC2, and NONO were identified and were demonstrated to be highly expressed in human breast cancer samples when compared to adjacent tissues using western blotting and quantitative reverse transcription polymerase chain reaction (qRT-PCR)." (PMID 34993131, 2021). "To further confirm whether COPS5, HDAC2, and NONO performed similar functions in normal and breast cancer cells, we measured the mRNA and protein levels in breast cancer and normal breast epithelial cells." (PMID 34993131, 2021). "Moreover, three hub TFs (COPS5, HDAC2, and NONO) were isolated as the prognostic biomarkers of breast cancer through the TF–target gene network, expression profile, and survival probability of the 10 prognosis-related TFs in breast cancer." (PMID 34993131, 2021).
lung carcinoma (23 papers, 2011 to 2025). "The overexpression of COPS5 is reported in many malignancies including lung cancer and associated with a poor prognosis." (PMID 38667328, 2024). "Increased levels of Jab1/COPS5 have previously been associated with shorter overall survival of lung cancer." (PMID 29228627, 2017). "Our results suggest that Jab1/COPS5 is associated with lung cancer progression, for example, stage, metastasis and malignant hydrothorax." (PMID 29228627, 2017). "For instance, COPS5 is overexpressed in several tumor types, and its overexpression is associated with short disease-free and overall survival in lung cancer." (PMID 21283576, 2011). "Here, we identified COPS5 as a deubiquitinating enzyme (DUB) of SNAIL to regulate the metastatic ability of lung cancer cells." (PMID 29755680, 2018). "Next, we tested the functional impact of COPS5 on lung cancer metastasis in vivo by using A549 cells expressing the firefly luciferase gene (A549/Luc2)." (PMID 29755680, 2018). "In agreement with our immunohistochemistry findings, the data from online database R2 indicated that COPS5 mRNA expression levels in lung cancer patients with stable disease are higher than those with complete response (right)." (PMID 29228627, 2017). "Although Jab1/COPS5 was found to be overexpressed in lung cancer, its role on therapeutic response remains to be determined." (PMID 29228627, 2017). "In the same way, UCHL1 and COPS5 were reported to be upregulated in lung cancer." (PMID 34577547, 2021). "The overexpression of COPS5 was related with decreased survival in patients with lung cancer." (PMID 34577547, 2021). "COPS5 regulates the invasiveness and metastasis of lung cancer cells." (PMID 29755680, 2018). "Besides lung cancer, COPS5 is overexpressed in many other types of cancer, including breast, pancreatic, and hepatocellular carcinoma." (PMID 29755680, 2018). "Their invasiveness were significantly suppressed by knocking-down of COPS5 in both H1650 and H2228 in concert with SNAIL reduction, suggesting the important role of COPS5 in the invasiveness of lung cancers independent of their specific oncogenic mutations." (PMID 29755680, 2018). "COPS5 expression was correlated with histological type (p=0.035), tumor stage (p=0.017), lymph node metastasis (p=0.016), distant metastasis (p=0.007) and hydrothorax status (p=0.039) in lung cancer patients." (PMID 29228627, 2017). "The prognostic value of Jab1/COPS5 was confirmed at the mRNA level by our analysis of independent publicly available microarray datasets, demonstrating a significant correlation between higher Jab1/COPS5 gene expression and reduced overall survival of lung cancer patients." (PMID 29228627, 2017). "Genes associated with cell immune functions were enriched in these pathways, such as COPS5, GSTM5, and TPI1, indicating the critical role of 5hmC modifications in immune response in lung cancer treatment." (PMID 38667328, 2024). "COPS5 downregulation significantly reduced the expression of SNAIL and impaired the metastatic potential of lung cancer cells both in vitro and in vivo." (PMID 29755680, 2018). "Strikingly, it is demonstrated that non-cancerous lung tissues showed significantly lower COPS5 expression than those in lung cancer tissues." (PMID 29755680, 2018). "Our study demonstrates that Jab1/COPS5 is upregulated in lung cancer tissue compared with non-cancerous tissue." (PMID 29228627, 2017). "It was found that lung cancer patients with no chemotherapy response had significant higher COPS5 expression than those with response (middle)." (PMID 29228627, 2017). "Lung cancer patients with increased Jab1/COPS5 level tend to be non-responsive to chemotherapy." (PMID 29228627, 2017).
hepatocellular carcinoma (17 papers, 2010 to 2025). A malignant tumor that arises from hepatocytes. "Jab1/COPS5 knockdown significantly inhibits proliferation and induces apoptosis in hepatocellular carcinoma cells." (PMID 31788446, 2019). "In hepatocellular carcinoma (HCC) cells, depletion of CSN5 (also known as COP9 signalosome subunit 5, COPS5) caused a significant decrease in glucose uptake and the production of glycolytic intermediates." (PMID 35307036, 2022).
pancreatic cancer (12 papers, 2008 to 2025). "It has been reported that polyethylene glycosylated curcumin (PEGylated curcumin), a water-soluble compound, inhibited pancreatic cancer cell growth by inhibiting Jab1/COPS5." (PMID 29535627, 2018).
colon carcinoma (11 papers, 2018 to 2025). "In particular, UBC, MCM2, and COPS5 show stronger dependencies in colon cancer comparing with the mean across all cell lines (six sigma or greater dependency)." (PMID 30723737, 2019). "Knockdown of Jab1/COPS5 significantly induced reduction of unphosphorylated Stat3 DNA-binding activity and Stat3 target genes, but nuclear Stat3 level was found increased in human colon cancer cell." (PMID 29535627, 2018).
nasopharyngeal carcinoma (10 papers, 2013 to 2024). A carcinoma arising from the nasopharyngeal epithelium. "Our previous animal studies also confirmed that suppression of Jab1/COPS5 signaling induces radio- and chemo-sensitivity in nasopharyngeal carcinoma." (PMID 29228627, 2017).
breast tumors (9 papers, 2008 to 2021). "In summary, in both clinical breast tumour samples and in vitro cell line models we observed that amplification and overexpression of COPS5 was associated with endocrine/tamoxifen-resistance." (PMID 27375289, 2016). "Intriguingly, while Jab1/COPS5 is significantly over-expressed in refractory tumors, NCoR is under-expressed in tamoxifen-resistant breast tumors." (PMID 29535627, 2018). "To evaluate if COPS5 protein overexpression is involved in tamoxifen-resistance, we investigated ERα+ breast tumours that were untreated (n=31) or refractory to tamoxifen-treatment (n=30)." (PMID 27375289, 2016). "Based on the immunohistochemistry (IHC) staining scores (refer to Methods), the rate of high expression (+ to +++) of COPS5 protein is significantly elevated in tamoxifen-refractory breast tumours (86.7%, 26/30) compared with untreated breast tumours (25.8%, 8/31)." (PMID 27375289, 2016). "Intriguingly, while COPS5 expressed significantly higher in refractory tumours (Pearson's χ2-test P<0.0001), it is also significant that NCoR expression is decreased in tamoxifen-resistant breast tumours (Pearson's χ2-test P=0.025)." (PMID 27375289, 2016). "Jab1/COPS5 expression was low in or absent from normal breast tissue, while it was abnormally expressed in breast tumors." (PMID 29383106, 2017).
colorectal cancer (9 papers, 2018 to 2025). A primary or metastatic malignant neoplasm that affects the colon or rectum. "Although little is known regarding the involvement of COPS5 in cancer metastasis, the role of COPS5 in the invasion of human colorectal cancer cell lines was previously studied." (PMID 29755680, 2018). "Furthermore, another DUB, COP9 signalosome subunit 5 (CSN5), is found in various cancers such as colorectal cancer." (PMID 33808323, 2021). "Additionally, a clear-cut reduction in β-catenin levels as well as its phosphorylated form has been observed in Jab1/COPS5 knock-down colorectal cancer cells, indicating that Jab1/COPS5 plays an important role in regulating β-catenin and the associated Wnt pathway." (PMID 29535627, 2018).
ovarian tumor (9 papers, 2011 to 2024). "Besides, Jab1/COPS5 was overexpressed in ovarian tumors and correlated with poor overall survival." (PMID 29535627, 2018).
cervical cancer (7 papers, 2018 to 2025). A primary or metastatic malignant neoplasm involving the cervix. "The methanolic extract of Moringa oleifera leaves suppresses the proliferation and causes the G1 arrest and apoptosis of cervical cancer cells by downregulating COPS5." (PMID 36612314, 2023). "Rutin, a bioflavonoid, induces the apoptosis of cervical cancer cells by downregulating COPS5." (PMID 36612314, 2023). "Although the effects of COPS5 knock-down in SNAIL expression was most predominant amongst the candidates in lung adenocarcinomas, the other four DUBs (JOSD1, OTUB1, OTUD7A, and OTUD7B) could potentially regulate SNAIL expression in other cancer such as cervical cancers." (PMID 29755680, 2018).
osteosarcoma (7 papers, 2010 to 2024). A usually aggressive malignant bone-forming mesenchymal neoplasm, predominantly affecting adolescents and young adults. "In one study, loss of COPS5 expression sensitized both mouse primary embryonic fibroblasts and osteosarcoma cells to radiation-induced apoptosis." (PMID 21755009, 2011).
ovarian carcinoma (6 papers, 2010 to 2024). A malignant neoplasm originating from the surface ovarian epithelium. "The xenografted mouse model was established to decipher the effect of COPS5 signaling on platinum resistance of ovarian cancer in vivo." (PMID 36135183, 2022). "To further verify the expression of COPS5 in platinum-resistant ovarian cancer, we constructed platinum-resistant ovarian cancer cell lines." (PMID 36135183, 2022). "In order to understand the potential therapeutic value of COPS5 in platinum-resistant ovarian cancer, we used Gene Expression Omnibus (GEO) datasets to find if there is any relationship between COPS5 and platinum resistance in EOC." (PMID 36135183, 2022). "COPS5 is related to multiple hallmarks of cancer and is overexpressed in multiple tumors, including breast and ovarian cancer." (PMID 33735170, 2021). "Therefore, we proposed that COPS5 participates in the heterogeneity of ovarian cancers, and in some patients, tumor cells with high COPS5 expression tend to be resistant to platinum and result in the formation of new metastasis." (PMID 36135183, 2022). "COPS5 inhibition is also sufficient to resensitize platinum-resistant ovarian cancer cells." (PMID 36135183, 2022). "COPS5 overexpression could define a group of patients with poor prognosis, which provides the rationale for COPS5 as a therapeutic target in platinum-resistant ovarian cancer." (PMID 36135183, 2022). "In vitro and in vivo experiments showed that COPS5 knockdown significantly sensitized EOC to platinum, which hinted that COPS5 inhibition is an effective and clinically relevant treatment for platinum-resistant ovarian cancer." (PMID 36135183, 2022).
liver cancer (5 papers, 2019 to 2024). An epithelial or non-epithelial malignant neoplasm that arises from the liver.
lung adenocarcinoma (5 papers, 2018 to 2025). A carcinoma that arises from the lung and is characterized by the presence of malignant glandular epithelial cells. "Because both A549 and Panc-1 are KRAS mutant cancer cell lines, we next checked the effects of COPS5 knock-down in H1650 or H2228 lung adenocarcinoma cell lines, which has an EGFR mutation or EML4-ALK fusion, respectively." (PMID 29755680, 2018). "The positive correlation between SNAIL and COPS5 expression was also relevant in the tissue microarray analysis of human lung adenocarcinoma panel." (PMID 29755680, 2018). "In alignment with our presented findings in the cell lines, the higher levels of COPS5 expression were correlated with SNAIL expression in the lung adenocarcinoma tissue samples as determined by the immunohistochemistry scoring." (PMID 29755680, 2018). "In addition to HCC, elevated COPS5 levels were associated with poor OS in breast invasive carcinoma (BRCA), kidney chromophobe (KICH), lung adenocarcinoma (LUAD), and pancreatic adenocarcinoma (PAAD)." (PMID 40198582, 2025). "Furthermore, the positive correlation between COPS5 and SNAIL expression is observed in the clinical tissue samples of lung adenocarcinomas using tissue microarray analysis." (PMID 29755680, 2018). "Furthermore, we observed the positive correlation between COPS5 and SNAIL expression in the clinical tissue samples of lung adenocarcinomas by using tissue microarray analysis." (PMID 29755680, 2018). "Finally, to explore the clinical relevance of the present findings, we examined the expression of COPS5 and SNAIL in the tissue microarray containing 160 lung adenocarcinomas." (PMID 29755680, 2018).
diffuse large B-cell lymphoma (4 papers, 2015 to 2024). "We further detected COPS5 as a potential upstream regulator of pathways associated with diffuse large B-cell lymphoma (DLBCL)." (PMID 38974382, 2024). "In particular, we identified COPS5 as a novel biomarker for diffuse large B-cell lymphoma (DLBCL) and experimentally validated by the CRISPR-Cas9 knockout, which supports the feasibility of our approach." (PMID 38974382, 2024).
leukemia (4 papers, 2007 to 2020). A malignant (clonal) hematologic disorder, involving hematopoietic stem cells and characterized by the presence of primitive or atypical myeloid or lymphoid cells in the bone marrow and the blood. "Suppression of Bcr-Abl by imatinib decreases Jab1/COPS5 expression in Bcr-Abl-positive leukemia cells." (PMID 29535627, 2018). "Bcr-Abl regulates Jab1/COPS5 by the cooperative interaction with β-catenin and Stat1 in leukemia cells." (PMID 29535627, 2018). "The oncogene Jab1/COPS5 is aberrantly expressed in several malignancies, including leukemia." (PMID 33292641, 2020).
glioma (3 papers, 2022 to 2023). A benign or malignant brain and spinal cord tumor that arises from glial cells (astrocytes, oligodendrocytes, ependymal cells). "For instance, the expression of COPS5 has a remarkably positive correlation with CNV in bladder urothelial carcinoma (BLCA), lower grade glioma (LGG), skin cutaneous melanoma (SKCM)." (PMID 37815881, 2023).
lymphoma (3 papers, 2015 to 2024). A malignant (clonal) proliferation of B- lymphocytes or T- lymphocytes which involves the lymph nodes, bone marrow and/or extranodal sites.
oral squamous cell carcinoma (3 papers, 2017 to 2024). "Researchers also showed that Jab1/COPS5 expression was closely linked to histological differentiation, lymph node metastasis, and clinical stage in oral squamous cell carcinoma." (PMID 29535627, 2018). "Indeed, accumulating evidence has shown the inverse association between Jab1/COPS5 and p27 expression in various human malignancies, including HCC, NPC, oral squamous cell carcinomas and papillary thyroid carcinoma." (PMID 29535627, 2018). "Patients with Jab1/COPS5 overexpression tended to have larger tumor size in thyroid carcinoma and poor overall survival in oral squamous cell carcinoma, NPC, and laryngeal squamous cell carcinomas, indicating its critical role in head and neck cancer." (PMID 29535627, 2018).
dementia (2 papers, 2022). Loss of intellectual abilities interfering with an individual's social and occupational functions. "BDNF expression is decreased in hippocampal and cortical neurons from 21-month APP/BIN1/COPS5 3xTg-AD mice, and is strongly reduced in buffy coat samples from patients with dementia or PD than in healthy control subjects." (PMID 35269588, 2022). "We previously demonstrated that DNMT1 mRNA levels are not regulated in buffy coat samples from patients with AD, whereas DNMT3a expression is downregulated in buffy coats from dementia patients and in the brain of saline-treated APP/BIN1/COPS5 AD mice." (PMID 36432638, 2022).
melanoma (2 papers, 2011 to 2017). A malignant, usually aggressive tumor composed of atypical, neoplastic melanocytes. "In the initial screening of melanoma samples, five genes (USP10, USP11, USP22, USP48 and COPS5) were significantly overexpressed, compared with benign nevi." (PMID 21283576, 2011). "We performed an in-depth analysis on four of them (COPS5 was not analyzed for the reasons mentioned in the previous paragraph) on a large melanoma case collection." (PMID 21283576, 2011).
Obesity (2 papers, 2025). Accumulation of substantial excess body fat. "In the obesity signature, eight genes were found to possess regulatory functions: COPS5, GATA2, MORF4L1, OPTN, PFDN5, SETBP1, TCF4, and ZBTB16." (PMID 40102990, 2025).